INS (insulin)
Diseases named in the same sentence as INS in open-access papers (continued):
Sharing a sentence is not in itself a finding about the gene and the disease.
Insulin resistance (continued). "In our study, the homeostasis model assessment of insulin resistance (HOMA-IR) was used to estimate insulin sensitivity." (PMID 22876749, 2012). "This insulin resistance occurrence in F group leads to both overproduction and secretion of insulin by the beta cells, then triggering the hyperinsulinemic state, as found during the oral glucose tolerance test." (PMID 22713601, 2012). "By using gold standard measures of insulin sensitivity, we demonstrated that insulin resistance is largely responsible for the relationship between plasma glucose levels and CVD risk." (PMID 22720085, 2012). "Hepatic insulin resistance impairs insulin’s ability to suppress hepatic glucose production (HGP) and contributes to the development of type 2 diabetes (T2D)." (PMID 22590537, 2012). "MFT has demonstrated positive associations with indices of insulin resistance (ie fasting blood glucose, HOMA-IR index, fasting serum insulin) and subclinical atherosclerosis (carotid intima-media thickness)." (PMID 23025515, 2012). "Protein-tyrosine kinase 1B (PTP1B) is a negative regulator of insulin signaling and is known to play critical role in insulin resistance." (PMID 23284633, 2012). "As a result, defective mitochondrial activity has been indirectly related to insulin resistance in insulin-targeted tissues, such as skeletal muscle and liver." (PMID 23236286, 2012). "We found a significant trend for increasing insulin levels and prevalence of insulin resistance across tertiles of MSG intake." (PMID 22681873, 2012). "As insulin resistance is considered a prediabetes stage and inflammation has been linked to the onset of this process, it might be expected to find higher levels of inflammation markers in obese patients that have developed T2D versus those obese people that keep an insulin resistant state." (PMID 23110196, 2012). "In fact, inhibition of protein tyrosine phosphatase 1B (PTP1B, a negative regulator of insulin signaling) activity ameliorates high-fat-diet-induced insulin resistance and lipid disorders in mice." (PMID 23304467, 2012). "Insulin sensitizing drug for example, metformin, provides benefit to control insulin resistance in PCOS women." (PMID 22737168, 2012). "Insulin resistance, or the failure of normal insulin-induced actions in major tissues including the liver, fat, and skeletal muscle, plays a key role in the pathophysiology of T2DM." (PMID 22969823, 2012). "The disease is characterized by a complex group of metabolic conditions, including inadequate insulin secretion by pancreatic islet cells and/or peripheral insulin resistance, and dysregulated hepatic glucose production." (PMID 24278747, 2012). "Conversely, impairment of brain insulin signaling (as occurs in peripheral insulin resistance) activates JNK, phosphorylating IRS-1 at Ser/Thr and promoting a feedback inhibition of IR, thus resulting in increased body weight." (PMID 22500228, 2012). "Serum fasting insulin and insulin resistance assessed by HOMA were positively correlated with fibrinogen (r = 0.26; P < 0.05), C-reactive protein (r = 0.29; P < 0.05, and r = 0.35; P < 0.01, resp)." (PMID 21822486, 2012). "Although there are several studies implicating increased protein-tyrosine phosphatase activity as contributing to insulin resistance, the evidence linking insulin signaling to zinc transport mechanisms and zinc-mediated signaling events is lacking." (PMID 23304467, 2012). "Many of them act as estrogens in insulin-sensitive tissues and in β cells, generating a pregnancy-like metabolic state characterized by insulin resistance and hyperinsulinemia." (PMID 22991565, 2012). "Insulin resistance, a whole mark of T2DM, is caused by the ‎‎inability of insulin-target tissues to respond properly to insulin, and in whose ‎‎etiology mitochondrial dysfunction is thought to play a crucial role." (PMID 22850324, 2012).
Insulin resistance (continued). "FFA have long been known to produce deleterious effects on pancreatic beta-cell function inhibiting insulin production and inducing insulin resistance whereas in parallel proinflammatory cytokines, such as TNF-α, alter insulin receptors." (PMID 22701480, 2012). "Elevated lipids, together with high plasma insulin levels, suggest unsuppressed lipolysis, indicative of adipose tissue insulin resistance." (PMID 22442717, 2012). "In this previous study, PLC decreases body weight gain, food intake, adiposity, insulin serum concentration and triglyceride liver content and improved insulin resistance." (PMID 22457831, 2012). "At baseline, genetic predisposition to T2D was associated with a lower acute insulin response, but also with a lower DI, which confirmed an impaired acute insulin response for the level of insulin resistance." (PMID 22350825, 2012). "Insulin increases hCAT-1 activity and expression in HUVECs, and A2AAR stimulation increases insulin sensitivity in subjects with insulin resistance." (PMID 22844517, 2012). "Tyrosine kinase inhibitors have been reported to decrease insulin resistance and increase insulin secretion in vitro." (PMID 22615750, 2012). "The pathogenesis of T2D in aging is characterized by two major features: peripheral insulin resistance and impaired insulin secretion from β cells." (PMID 22675349, 2012). "Diets producing a high glycemic response result in exaggerated insulin secretion which induces hepatic lipogenesis, contributing to development of insulin resistance and fatty liver." (PMID 23146593, 2012). "It has been shown that RBP4 is associated with variables related to insulin resistance and diabetic complications; an increased level of plasma RBP4 increases insulin resistance by inhibiting insulin signaling." (PMID 22568928, 2012). "Increased proteolysis in insulin resistance and DM has been reported, most likely from the removal of the anti-catabolic effect of insulin." (PMID 22546713, 2012). "IR/LepRPOMC mice also show significantly increased basal insulin levels, reduced glucose tolerance, overall insulin resistance, and profound hepatic insulin resistance resulting in increased glucose production." (PMID 23119079, 2012). "Some strategies to alleviate insulin resistance by nutritional supplements appear to improve insulin sensitivity in many individuals and improve glycemic control in diabetics." (PMID 22483164, 2012). "In contrast, the pathophysiological scheme that is generally considered by the contemporary scientific community to explain T2D begins with a gradual attenuation in the response of tissues to insulin, called insulin resistance." (PMID 22235232, 2012). "In contrast, OA improves insulin signaling and protects against PA-induced insulin resistance in L6 myotubes." (PMID 22623960, 2012). "Data to support a role for TNF-α in the genesis of insulin resistance found in insulin resistant transgenic mice infected with hepatic C core protein." (PMID 23049551, 2012). "The most notable characteristic of Cdkal1−/− mice is the reduced fat accumulation with high-fat-fed intervention, accompanied by protection against insulin resistance (or in other words, enhanced insulin sensitivity)." (PMID 23173044, 2012). "Protein tyrosine phosphatase 1B (PTP1B), a key negative regulator of leptin and insulin signaling, is positively correlated with adiposity and contributes to insulin resistance." (PMID 22389718, 2012). "In contrast, chronic hyperinsulinemia contributes to a combination of hepatic insulin resistance in which the insulin-dependent activation of lipogenic gene expression remains intact, but gluconeogenic gene expression is inadequately repressed." (PMID 23110872, 2012). "Secondly, high-fat maintenance throughout gestation and postnatal life resulted in a severe obese phenotype characterized by the highest body weights, leptin and insulin concentrations, and most severe insulin resistance in male offspring." (PMID 22988521, 2012).
Insulin resistance (continued). "In mice, transgenic expression of RBP-4 caused insulin resistance, and RBP-4 knockout mice display enhanced insulin sensitivity." (PMID 22272381, 2012). "The excess of lipids is shunted to the liver and skeletal muscle, which results in impaired insulin signalling within these tissues and consequent development of insulin resistance." (PMID 22823902, 2012). "All subjects had some degree of glucocorticoid-induced hyperglycemia and insulin resistance following dexamethasone treatment, with a significant increase in fasting glucose, insulin and HOMA2-IR homeostasis model assessment." (PMID 23241228, 2012). "Insulin resistance is an impaired response to insulin in specific organs or cells such as liver, fat and muscle, and is strongly associated with the development of obesity and type 2 diabetes." (PMID 22409911, 2012). "Together these results suggest that insulin resistance in ob/ob mice can be compensated by increased insulin secretion, which is particularly observed in aged mice when glucose tolerance improves while insulin secretion increases." (PMID 22829877, 2012). "In preclinical models of insulin resistance, improvements in insulin sensitivity, especially in hepatic insulin sensitivity, have been noted in animals treated with SGLT2 inhibitors." (PMID 22355316, 2012). "Only one SNP, rs3743462, showed trends of association with lower fasting insulin plasma concentrations, lower indices of basal insulin secretion (HOMA-B) and insulin resistance (HOMA-IR) (P≤0.002)." (PMID 22606236, 2012). "Elevated insulin levels with corresponding insulin resistance and elevated blood glucose have been correlated with poor outcomes in breast cancer patients." (PMID 23050155, 2012). "The present study aimed to investigate the effect of a fraction from wax apple fruit extract (FWFE) on alleviating insulin resistance in TNF-α treated insulin resistant FL83B mouse hepatocytes." (PMID 22942720, 2012). "Acute exercise significantly enhanced insulin’s ability to stimulate glucose absorption in skeletal muscle and counteracted insulin resistance, a typical feature of type 2 diabetes." (PMID 23272147, 2012). "High fat feeding in rodents generally leads to obesity and insulin resistance whereas in humans this is only seen if dietary carbohydrate is also high, the result of the anabolic effect of poor regulation of glucose and insulin." (PMID 22838969, 2012). "In humans, insulin resistance was induced by infusion of high concentrations of amino acids, whereas the mTORC1 inhibitor rapamycin improved insulin action." (PMID 22891897, 2012). "TZDs are used to improve insulin sensitivity, but they have also been studied for their potential to prevent insulin resistance." (PMID 22726273, 2012). "In the setting of insulin resistance, the vasodilatory effect of insulin can be lost, but the renal effect on sodium reabsorption preserved." (PMID 22523674, 2012). "HCQ use for 6 weeks in non diabetic obese subjects was associated with a significant increase in ISI and trends toward reduced insulin resistance and insulin secretion." (PMID 22676348, 2012). "Chronic high glucose (HG) inflicts glucotoxicity on vulnerable cell types such as pancreatic β cells and contributes to insulin resistance and impaired insulin secretion in diabetic patients." (PMID 23024780, 2012). "Homeostasis model assessment of insulin resistance (HOMA-IR) was used as an indicator of insulin resistance and was defined as follows: fasting insulin (μIU/mL) × fasting plasma glucose (mmol/L)/22.5." (PMID 22691278, 2012). "Low grade systemic inflammation and insulin resistance often occur together, and adipose tissue is a site of inflammation in the insulin resistant state." (PMID 22974251, 2012). "It has been demonstrated that an increase in plasma lipid levels leads to a decrease in hepatic insulin clearance, which results in insulin resistance and hyperinsulinemia." (PMID 23346150, 2012).
Insulin resistance (continued). "TNF-α contributes insulin resistance by blunting the insulin-stimulated tyrosine phosphorylation of IRS-1, inhibiting glucose uptake, and activating NFκB pathway." (PMID 22778500, 2012). "Studies in adult population have shown that parameters of insulin sensitivity and insulin resistance as calculated by hyperinsulinemic euglycemic clamp study (M value) correlated better with serum 25(OH)D levels than indirect parameters like HOMA-IR." (PMID 22966228, 2012). "Another difference is that whereas most RA patients have increased basal plasma insulin levels and insulin resistance, arthritic rats have lower serum insulin levels." (PMID 23781298, 2012). "Insulin resistance is broadly defined as the reduction in insulin ability to stimulate glucose uptake from body peripheral tissues." (PMID 22360800, 2012). "The clamp study showed that DIO mice injected with NPB112 at 5 mg/kg were more insulin sensitive than control mice, indicating amelioration of insulin resistance by treatment with NPB112." (PMID 23226550, 2012). "Insulin resistance refers to impaired insulin sensitivity and glucose metabolism, and commonly precedes development of DM." (PMID 22676348, 2012). "Using palmitic acid as an inducer of insulin resistance, we tested the anti-insulin resistant effects of several fatty acids." (PMID 22409911, 2012). "Insulin resistance and insulin secrete defection are two important factors in the pathogenesis of T2DM." (PMID 21716678, 2012). "It has moreover been demonstrated that overexpression of RBP-4 in normal mice increases insulin resistance, whereas genetic disruption of this adipokine increases insulin sensitivity." (PMID 22550485, 2012). "The presence of insulin resistance using the increased baseline insulin or insulin elevation over 100 mU/L during the OGTT correlates better with the arterial blood pressure and lipid levels than when using elevation of IRI more than 5 times over the baseline." (PMID 22262974, 2012). "Insulin resistance has traditionally been defined by defective insulin action resulting in fasting hyperinsulinemia." (PMID 22523674, 2012). "First, overeating and/or obesity lead to the development of insulin resistance, and normal β-cells secrete a larger amount of insulin to compensate for the increased insulin resistance." (PMID 23202973, 2012). "Compensatory adaptations of insulin secretion for insulin resistance have been reported to change over time in the high fat–fed mouse model during long-term (∼40 weeks after initiation of high-fat diet) studies." (PMID 23173044, 2012). "Defects of insulin signaling therefore result in insulin resistance, alterations in glucose tolerance, and vascular endothelial dysfunction, which is often seen in the metabolic syndrome, a cluster of cardiovascular risk factors." (PMID 22934083, 2012). "Several animal models corroborate this view and suggest that selective insulin resistance in adipocytes can be otherwise considered an etiological factor leading to improved systemic insulin responsiveness and protection against HFD-induced obesity." (PMID 23024762, 2012). "Obesity has been shown to be associated with the activation of the innate immunity pathway and inflammatory response, as well as an impaired insulin signaling pathway and insulin resistance." (PMID 23251812, 2012). "Transgenic overexpression of GLUT4, either under the control of the native promoter or a tissue-specific, heterologous promoter, led to enhanced insulin sensitivity, enhanced glucose clearance, and provides some protection against insulin resistance." (PMID 27335671, 2012). "HFD-induced insulin resistance in rats reduced insulin’s ability to stimulate PKCζ/λ activity, even though the phosphorylation and protein expression levels of PKCζ and PKCλ remained unchanged." (PMID 23272147, 2012).
Insulin resistance (continued). "Berberine has shown significant results in fasting blood glucose levels reduction, increase in insulin sensitivity, and improvement in insulin resistance in vitro, in diabetic animal models and in diabetic patients." (PMID 23213296, 2012). "Activation of α7-nAChR not only improves insulin sensitivity in normal mice but also AMPKα2−/− mice, an animal model of insulin resistance." (PMID 23251458, 2012). "Activation of α7-nAChR also improved insulin sensitivity in AMPKα2−/− mice, a model of insulin resistance." (PMID 23251458, 2012). "Further studies detected a correlation between increasing insulin resistance and fasting insulin level, with PRL." (PMID 22405326, 2012). "The present study reveals that the removal of maternal melatonin during pregnancy and lactation by means of pinealectomy predisposes male and female offspring to glucose intolerance arising from hepatic insulin resistance and decreased insulin secretion." (PMID 22719949, 2012). "We utilized IVGTT to assess both glucose tolerance and insulin resistance as well as the acute insulin response and glucose disposition indices that better define the beta-cell function." (PMID 22643321, 2012). "Insulin resistance promotes lipolysis, and lipolysis generates toxic lipids, that is, ceramides, which further impair insulin signalling, mitochondrial function, and cell viability." (PMID 22701480, 2012). "In this regard, two recent publications have established that direct AT2 receptor stimulation with C21/M024 improves insulin sensitivity in a rat model of diet-induced insulin resistance and in type 2 diabetic mice." (PMID 23320146, 2012). "Type 2 diabetes (T2D) results from a combination of insulin resistance and impaired ability of the pancreatic beta-cell to secrete sufficient insulin." (PMID 22350825, 2012). "The levels of plasma ghrelin are negatively correlated with body weight, fasting insulin levels, and insulin resistance (HOMA-IR) and are positively correlated with the insulin sensitivity index (ISI)." (PMID 23251812, 2012). "This promotes spill-over of free fatty acids to skeletal muscle and liver and ectopic lipid deposition in these tissues which promotes insulin resistance and reduced insulin-stimulated muscular glucose uptake." (PMID 22457810, 2012). "High fasting insulin or glucose is an indicator of insulin resistance and the insulin-glucose product was increased by 82% (p = 0.02) and 94% (p = 0.01) in low fat diet and high fat diet fed Spd−/− mice, respectively." (PMID 22509382, 2012). "Resolution of endogenous and load contributions to PGE by [U-13C]glucose and 2H2O informs the response of hepatic glucose metabolism to insulin and hepatic insulin resistance." (PMID 22479514, 2012). "Increased CD36 expression has been shown to contribute to dyslipidemia and to be associated with insulin resistance and decreased glucose tolerance, suggesting that CD36 is involved in the physiopathology of insulin sensitivity." (PMID 22662181, 2012). "Insulin resistance results in elevated glucose levels and a compensatory insulin increase which will further deteriorate insulin sensitivity." (PMID 22983440, 2012). "This review is focused on the mechanistic aspects of the insulin-induced H2O2 signalling pathway in neurons and the molecules affecting it, which act as risk factors for developing central insulin resistance." (PMID 23730255, 2012). "Physical exercise has been widely used to protect the body against the decreased responses to the biological actions of insulin in peripheral tissues and to reduce the metabolic changes that are produced by insulin resistance." (PMID 23067133, 2012). "Large dosages of chungkookjang reportedly exert anti-diabetic effects by potentiating glucose-stimulated insulin secretion and attenuating insulin resistance." (PMID 23270397, 2012). "All of these intermediates correlate with insulin resistance and directly alter the insulin signaling cascade described previously." (PMID 22474580, 2012).